EIF4E (eukaryotic translation initiation factor 4E)
Diseases named in the same sentence as EIF4E in open-access papers (continued):
Sharing a sentence is not in itself a finding about the gene and the disease.
tumor (continued). "Interestingly, higher activity of eIF4E in the tumor margin, even those free of microscopic tumor, is an independent predictor of local recurrence while histological grading of dysplasia failed to predict prognosis." (PMID 21513566, 2011). "It is known that eIF4E acts oncogenically if overexpressed, resulting in tumor growth." (PMID 21399233, 2011). "Interestingly however, VSV infection results in reduction of eIF4E phosphorylation, shortly preceding the shut-off of host protein synthesis in tumor cell lines." (PMID 20539760, 2010). "This suggests that molecular events such as eIF4E gene amplification may precede cellular morphological changes, and that surgical margins which appear tumor free microscopically, may have elevated eIF4E protein levels." (PMID 20049173, 2009). "The alteration in global translation rates may be due to a larger pool of mRNAs that are discriminated by eIF4E in tumor cells." (PMID 19401772, 2009). "The oncogenic role of this overexpression has been shown by various experimental observations; for example, forced eIF4E overexpression within many cell types leads to transformation, and within transgenic mice increases incidence of multiple tumour types." (PMID 19367274, 2009). "Notably, many researchers have shown that hyperactive eIF4E in tumors mostly enhances the translation of proteins which are involved in tumor progression such as Bcl-2, survivin, cyclin D1, C-myc, and VEGF." (PMID 22649602, 2009). "The decreased eIF4E expression seen in tumour-bearing rats suggested that there was less translation and, consequently, less protein synthesis since eIF4E is necessary for assembly of the eIF4G-eIF4E complex which modulates the overall rate of protein synthesis." (PMID 17341295, 2007). "Potentially, the ratio of 4E-BP to eIF4E may determine whether inhibition of mTOR elicits a biologically significant tumour response." (PMID 16953237, 2006). "A number of observations suggest that increased expression of eIF4E might be one of the key elements leading to angiogenesis, which ultimately results in tumor metastasis." (PMID 17010208, 2006). "In addition to decreased 4E-BP1 expression, increased eIF4E expression in mice is tumorigenic and increases the rate of tumour progression." (PMID 16953237, 2006). "Furthermore, the importance of eIF4E's role in tumorigenesis is reinforced by the finding that eIF4F complex is necessary for maintaining tumour cell growth." (PMID 16404421, 2006). "Expression of the eukaryotic initiation factor-4E (eIF-4E), a factor implicated in the translational regulation of VEGF, was greater in tumours than normal bladder (P< 0.0001) and correlated with VEGF protein:mRNA ratios (n = 43, r = 0.54, P = 0.0004) pointing to its role in the regulation of VEGF." (PMID 10638984, 2000). "However, many cell types, including tumor cells, frequently experience environmental stress such as hypoxia, nutrient deprivation, or proteotoxic stress, all of which can inactivate mTORC1 and suppress eIF4E activity." (PMID 41522609, 2026). "We also wanted to explore whether JDB153 would influence eIF4E's phosphorylation in tumor cells." (PMID 40308810, 2025). "Indeed, ribavirin has demonstrated anti-tumour activity in preclinical studies and therapeutic benefit in clinical trials, but its efficacy may involve mechanisms unrelated to eIF4E." (PMID 40805230, 2025). "Degradation of MNK1/2 further affected phosphorylation of eIF4E adversely, which in turn restricted mRNA 5’cap-mediated translation initiation thereby checking uncontrolled protein synthesis in tumor cells, effectively restricting tumor growth and proliferation." (PMID 37766871, 2023). "The precise effect of eIF4E phosphorylation on mRNA translation is still not fully clear, but it appears to promote the translation of some mRNAs, including ones encoding proteins involved in tumour metastasis." (PMID 37143925, 2023).
tumor (continued). "Finally, using eIF4E as a molecular target for tumor therapy, establishing models that multiple anti-tumor drugs are used in combination may provide new ideas for improving the efficacy and reducing side effects." (PMID 37601696, 2023). "Eukaryotic initiation factors (eIFs) consisting of eIF4E, eIF2, eIF6 and so on are the main regulators in the initial stage of mRNA translation, whose abnormal expression has been confirmed to be involved in tumor progression, including proliferation, anti-apoptosis, and metastasis." (PMID 35737644, 2022). "Unlike the overexpression of eIF4E, which directly stimulates tumor initiation, eIF4E phosphorylation facilitates tumor progression through the translation of a selective subset of mRNAs critical for extracellular remodeling, metastasis, and tumor inflammation." (PMID 33382175, 2021). "In addition, further correlation analysis between eIF4E and immune markers showed that eIF4E could regulate the tumor infiltrating immune cell pattern in the TME of BRCA." (PMID 34876062, 2021). "In addition, inhibition of eIF4E reduces tumor growth and malignancy in experimental models." (PMID 32340135, 2020). "Importantly, tumor cells with over-expressed eIF4E may develop an addiction to eIF4E, making these cells vulnerable to eIF4E inhibition, whereas non-malignant cells are resistant." (PMID 32708122, 2020). "Furthermore, a dominant negative MNK1 mutant which is unable to phosphorylate eIF4E inhibited the in vivo proliferation of tumor cells promoted by mutations that lead to the deregulation of protein synthesis." (PMID 33148274, 2020). "Hence, like eIF4E and eIF4G, eIF3h also affects protein synthesis and tumor aggressiveness." (PMID 32708122, 2020). "Interestingly, multivariate analysis revealed that eIF4E intensity in tumours was an independent prognosticator for relapse‐free survival (RFS) and was significantly associated with clinic ‐pathologic features (serum alpha‐fetoprotein level, gamma glutamyl transferase, vascular invasion of HCC)." (PMID 30677218, 2019). "With the eukaryotic translation initiation factor 4E (eIF4E), a protein was found whose expression was triggered by conditioning with secretome of activated PSCs and which is involved in the control of many of the identified protein variations in the tumour cells." (PMID 30923340, 2019). "Indeed, eIF4E phosphorylation by MNK1/2 and p38 MAPKs is required for its oncogenic role by translation of a subset of mRNAs encoding proteins involved in survival and tumor invasion." (PMID 31684984, 2019). "PI3K activity is often high in tumors due to the loss of the PTEN tumor suppressor, which allows a constitutive activation of AKT kinase, inappropriate mTORC1 signalling, phosphorylation and inactivation of 4EBP1 and, consequenltly, eIF4E available to be phosphorylated by MNK1." (PMID 29568373, 2018). "Overexpression or knockdown of eIF4E by RNA intervention modulated tumor cell growth and chemosensitivity to cisplatin both in vitro and in vivo, which suggested that eIF4E might have a great potency of synergistic effect of cisplatin to ameliorate drug resistance in ESCC and many other tumors." (PMID 27588477, 2016). "Furthermore, we found that overexpression of eIF4E promoted tumorigenicity in vivo when compared to blank control mice (P = 0.045), while knockdown of eIF4E significantly decreased the primary tumor size (P = 0.032)." (PMID 27588477, 2016). "Targeting eIF4E for inhibition may provide an attractive therapy for many different tumor types." (PMID 27588477, 2016). "Moreover, the analysis of clinical CRC tumor tissues indicates that there is a positive association between 4E-BP1 and eIF4E protein expression, suggesting that eIF4E may have a similar role as 4EBP in CRC tumorigenesis." (PMID 26204490, 2015). "Therefore, it is a promising drug to treat tumor cells with over-expressed eIF4E." (PMID 26317515, 2015).
tumor (continued). "In addition to conferring mTOR inhibitor resistance, a reduced 4EBP:eIF4E ratio might help to drive the tumor phenotype by facilitating translation of oncogenic mRNAs." (PMID 24586420, 2014). "Using this hypothesis, one would predict that tumours with high pre-treatment estimated eIF4E activities would be most subject to drug-induced expression changes or to clonal selection pressures, and would show the greatest adaptive changes in eIF4E regulation." (PMID 21320304, 2011). "Our hypothesis was that these changes represent development of acquired resistance to inhibition of eIF4E activity, by induction of changes in eIF4E regulation within tumour cells or by clonal selection of cells with different eIF4E-related expression profiles." (PMID 21320304, 2011). "Also, there was a progressive increase in the degree of eIF4E gene amplification and protein expression when comparisons were made among samples from tumor free margins of resected carcinoma specimens, tumor free regions adjacent to tumor core and tumor core samples." (PMID 20049173, 2009). "In this way, the hypoxia that accompanies tumor growth may stimulate eIF4E expression." (PMID 20049173, 2009). "The observation that both domains of FUS-DDIT3 are required to regulate eIF4E expression provides the first molecular evidence that the FUS component of the fusion protein is required not only for transformation but also influences the phenotype of the tumor cells." (PMID 18596980, 2008). "In addition, we found that overexpression of eIF4E might play an important role in tumor progression and microneoangiogenesis." (PMID 17010208, 2006). "RNA‐sequencing (RNA‐seq) and pathway analyses showed that upregulated EIF4E activated Wnt signalling and extracellular matrix (ECM) components, processes required for tumour progression." (PMID 40842081, 2025). "We found that MYC, E2F1, and EIF4E are all positively correlated with PRMT5 and KRAS with an R-value > 0.70 and a p-value < 0.01 in CRC patient tumor samples." (PMID 40864819, 2025). "In tumours, the overexpression of MYC activates RNA polymerase I (Pol I) and III (Pol III) and translation initiation factors such as eIF4E, enhancing protein synthesis and promoting metabolic reprogramming." (PMID 40525649, 2025). "Further studies have also demonstrated that silvestrol sensitises tumours with PTEN inactivation and elevated eIF4E to doxorubicin in vivo." (PMID 40805230, 2025). "On the contrary, other signature genes (e.g., EIF4E, MAP4K1) were shown to be highly expressed in tumor samples, supported by their functions in either mTOR or Hippo regulations." (PMID 38468074, 2024). "It’s found that IHC signals of BNIP3, CYCS, RRAGD, CD44, EIF4E, and MAP4K1 were consistently high in tumor cells of HCC, compared with normal tissues, implying that these genes were indeed ectopically expressed in HCC." (PMID 38468074, 2024). "Results showed that the mRNA levels of BNIP3, CYCS, RRAGD, CD44, EIF4E, MAP4K1, and LIN28B were higher in tumor samples, whereas the mRNA levels of PPARGC1A and FLT3 were higher in normal samples." (PMID 38468074, 2024). "We further found the expressions of eIF4E and NFAT1 were significantly upregulated in GC tumor tissues than normal mucosa respectively in the GEPIA database." (PMID 38448411, 2024). "By exporting oncoprotein mRNA complexes with eukaryotic translation initiation factor 4E (eIF4e) out of the nucleus, XPO1 contributes to the elevation of oncoprotein levels, fostering tumor growth and survival." (PMID 38927948, 2024). "Immunoblotting analysis of key proteins in the excised tumor tissue revealed significant downregulation of MNK1, accompanied by a decrease in p-eIF4E, which can be attributed to elevated levels of SYVN1 compared to the control." (PMID 37766871, 2023).
tumor (continued). "Numerous studies have found that m7G regulator hub genes (EIF4E, EIF4E3, EIF4E2, NCBP1, and NCBP2) are crucial in tumor progression and metastasis." (PMID 36998056, 2023). "These pathways can be categorized into tumor-related pathways (AKT/mTOR and c-Met) and translation-related pathways (eIF4E release and cap-dependent mRNA activation factors)." (PMID 38072995, 2023). "According to the research on non-small cell lung cancer, PM2.5 upregulated the expression of DLAT to promote glycolysis through the dual regulation mechanism of Sp1-DLAT and eIF4E-DLAT axis, enhancing the proliferation of tumor cells." (PMID 36925927, 2023). "Phosphorylation of eIF4E by MNK1/2 is a critical step in mRNA 5’cap-dependent translation of many proteins that actively promote cell division and tumor growth." (PMID 37766871, 2023). "Three-dimensional culture of tumor cells and HUVECs showed that necroptotic conditioned medium promoted tumor cell and HUVEC tube formation, while knockdown of eIF4E blocked VM formation during necroptosis." (PMID 37217473, 2023). "Preventing phosphorylation of eIF4E in BRAFV600; PTEN KO transgenic mouse models also results in the increased expression of MART-1 and gp100 by tumor cells and their recognition and eradication by CD8+ T cells." (PMID 35432344, 2022). "As another member of the IGF2BP family, IGF2BP3 reportedly promotes eIF4E‐mediated translational activation by decreasing the stability of EIF4E‐BP2 mRNA, which in turn enhances the proliferation of tumour cells." (PMID 35876041, 2022). "We found that the tumorigenesis of the eIF4E-knockdown Molm13 and NB4 cells was impaired, as shown by a significant decrease in tumor size and weight." (PMID 36365147, 2022). "Eukaryotic translation initiation factor 4E (eIF4E) is the target of the most vital signaling pathways, PI3K/Akt/mTOR and RAS/MAPK in PCa, which mediate the tumor progression." (PMID 35677157, 2022). "More than half of the m7G-related genes were significantly upregulated in tumor samples, such as METTL1, WDR4, EIF4E, LARP1, and LSM1." (PMID 36761423, 2022). "While hyperphosphorylation of eIF4E is shown to be a rather early event during CRC carcinogenesis, eIF4E overexpression is a progressive process throughout tumor development." (PMID 33382175, 2021). "c-Myc, as an oncogene, and its target genes, including eukaryotic translation initiation factor 4E (eIF4E) and Cyclin-Dependent Kinase 4 (CDK4), are silenced following the miR-145 upregulation, which leads to tumor suppression." (PMID 34307654, 2021). "In CRC, the specific inhibition of MNK1/2, and thereby the inhibition of eIF4E phosphorylation, results in reduced tumor cell viability and tumor growth, suggesting the importance of the MNK/eIF4E axis in CRC tumorigenesis." (PMID 33382175, 2021). "Meanwhile, eIF4E can also be regulated by mitogen-activated protein kinase (MAPK) pathways, which is involved in the development and progression of tumor." (PMID 32023262, 2020). "Cabozantinib, another MET/multikinase inhibitor with MNKs as direct targets, exhibited anti-tumor activity in vitro and in a genetically engineered mouse MPNST model by suppressing eIF4E phosphorylation." (PMID 32340135, 2020). "Overall, MNK2 promotes tumor proliferation, migration, invasion and metastasis in NSCLC in vitro and in vivo via 4EBP1/eIF4E and ERK/eIF4E pathway." (PMID 28878291, 2017). "Emerging evidence has shown that EIF4E, especially its phosphorylated form is up-regulated in NSCLC tumor tissues, which is correlated with a shorter survival and increased lymph node metastasis." (PMID 28903455, 2017). "Another study confirms that knock-down of EIF4E or EIF4G1 prevents NSCLC cell migration and epithelial-to-mesenchymal transition (EMT), which represent essential steps for tumor metastasis." (PMID 28903455, 2017). "They position 4E-BP1 as a tumor-specific target of HCV core and support the involvement of the 4E-BP1/eIF4E axis in hepatocarcinogenesis." (PMID 28915586, 2017).
tumor (continued). "BEZ235 displayed a statistically significant anti-tumor activity and synergy with IR against OML1-R xenografts and an attenuation effect of eIF4E and S6K phosphorylation." (PMID 28978144, 2017). "It has recently been demonstrated that at the early stages of tumor development MYC not only enhances the overall protein synthesis but also specifically activates mTOR-mediated 4EBP1 phosphorylation, leading to eIF4E oncogene activation." (PMID 28187001, 2017). "Since previous studies indicate that HIF-2α promotes the growth, invasion, and angiogenesis of tumor cells, we further investigated the effects of miR-558 over-expression and knockdown of AGO2, eIF4E, or HIF-2α on cultured NB cells." (PMID 27276678, 2016). "We next investigated the efficacy of miR-558 over-expression and knockdown of AGO2, eIF4E, or HIF-2α against tumor growth, metastasis and angiogenesis in vivo." (PMID 27276678, 2016). "eIF4E knockdown by shRNA increased cisplatin-induced cytotoxicity in ESCC cell lines, and enhanced chemosensitivity to cisplatin in xenograft tumor models." (PMID 27588477, 2016). "Similarly, EIF4EBP1, as the repressor of EIF4E, also may act as tumor promoter or tumor inhibitor." (PMID 25658620, 2015). "Thus the higher levels or activity of eIF4E often found in tumour cells may not only enhance the synthesis of growth-promoting or anti-apoptotic proteins (translated from relatively “weak” mRNAs) but also desensitize the cells to physiological stresses and the inhibition of mTOR." (PMID 23940704, 2013). "Expression levels of eIF4E, 4E-BP1, 4E-BP2 and Thr37/Thr46 phosphorylated 4E-BP1 (phospho-4E-BP1) within tumour cells were determined semi-quantitatively in matched pre- and post-treatment tumour samples from 22 patients using immunohistochemistry." (PMID 21320304, 2011). "The prediction of recurrence by expression of eIF4E in HNSCC margin is independent from tumor size, nodal status, stage, histologic grade, tumor site, eIF4E levels in the tumor, and with the degree of dysplasia in the margins." (PMID 21513566, 2011). "This complex is regulated by the 4EBP1, a translational repressor that inhibits the function of eukaryotic translation initiation factor 4E (EIF4E), which compete with EIF4G1 for binding to eIF4E and have tumor-suppressor activity." (PMID 20398343, 2010). "We carried out IHC for eIF4E, 4E-BP1, 4E-BP2 and p4E-BP1 on TMA sections and assessed immunoreactivity within tumour cells, taking into account the proportions of cells staining positively and average intensity, giving scores of 0 (negative) or 2–7 (positive)." (PMID 19367274, 2009). "We believe that a potential linkage of high eIF4E expression results in the upregulation of angiogenic factors such as VEGF, creating the subsequent increase in tumor MVD and a worse clinical outcome." (PMID 17010208, 2006). "The eIF4E, MVD, and tumor stage still emerged as independent prognostic factors (p = 0.02, p = 0.011, and p = 0.048, respectively), but node metastasis was found to be of borderline significance (p = 0.062)." (PMID 17010208, 2006). "Real-time quantitative RT–PCR analysis was performed on mRNA transcripts of nine genes (VEGF121, VEGF165, VEGF189, VEGF-C, eIF-4E, b-FGF, TSP-2, MMP-2 and MMP-9) involved in angiogenesis and/or lymphangiogenesis as well as tumour cell invasion." (PMID 12189553, 2002). "In tumours, the abnormal expression of the PI3K/Akt/mTOR pathway activates downstream signalling, such as the phosphorylation of 4E‐BP1, leading to the release of the eukaryotic translation initiation factor eIF4E and promoting protein translation." (PMID 40525649, 2025).